RDH13 (retinol dehydrogenase 13)
Description:
Retinol dehydrogenase with a clear preference for NADP. Oxidizes all-trans-retinol, but seems to reduce all-trans-retinal with much higher efficiency. Has no activity toward steroids.
Synonyms: SDR7C3
Tractability: Antibody: UniProt places it where antibodies can reach, with high confidence. PROTAC: ubiquitination databases record sites on it; its protein half-life has been measured.
Gene: Protein-coding gene on chromosome 19 (55,039,108 to 55,071,291, reverse strand). Ensembl gene ENSG00000160439.
Subcellular location: Mitochondrion inner membrane
Subcellular location (Human Protein Atlas): Cytosol; Mitochondria
Pathways (Reactome):
Signal Transduction: RA biosynthesis pathway
Gene Ontology:
Molecular function: all-trans-retinol dehydrogenase (NADP+) activity
Biological process: retinal metabolic process; eye photoreceptor cell development; retina layer formation; retinol metabolic process
Cellular component: mitochondrial inner membrane; mitochondrion
Genetic constraint (gnomAD): Loss-of-function variants: 35 observed, 30.38 expected, observed/expected ratio (o/e) 1.15, 90% interval 0.88 to 1.53. The upper end of that interval is the gene's LOEUF score, 1.53, which puts it in group 6 of 6, group 1 being the genes least tolerant of losing a copy. Missense variants: 491 observed, 414.82 expected, observed/expected ratio (o/e) 1.18, 90% interval 1.1 to 1.27. Synonymous variants: 222 observed, 185.04 expected, observed/expected ratio (o/e) 1.2, 90% interval 1.08 to 1.34.
Homologues: Orthologues: chimpanzee RDH13 (99% identical), macaque RDH13 (97% identical), guinea pig RDH13 (87% identical), pig RDH13 (86% identical), mouse Rdh13 (84% identical), dog RDH13 (73% identical), tropical clawed frog rdh13 (72% identical), rat Rdh13 (70% identical), rabbit RDH13 (58% identical), Caenorhabditis elegans E04F6.15 (29% identical), Caenorhabditis elegans dhs-7 (29% identical), Caenorhabditis elegans DC2.5 (27% identical), and 3 more. Paralogues in human: RDH14 (48% identical), DHRS13 (42% identical), DHRSX (38% identical), KDSR (23% identical).
Diseases named in the same sentence as RDH13 in open-access papers:
RDH13 is named in the same sentence as 11 diseases in open-access papers, as found by Europe PMC text mining. Sharing a sentence is not in itself a finding about the gene and the disease. The quoted sentences say what the papers report.
preeclampsia (3 papers, 2014 to 2026). Preeclampsia is a hypertensive disorder of pregnancy that is characterized by new-onset hypertension with proteinuria presenting after 20 weeks of gestation, and depending on mild or severe forms may initially present with severe headache, visual disturbances, and hyperreflexia. "RDH13 encodes a mitochondrial short-chain dehydrogenase/reductase and its association with preeclampsia has been identified in several previous studies." (PMID 35774506, 2022). "RDH13 was identified as a candidate functional mediator of miR-142-3p based on its intersection with miR-142-3p targets, DEGs, and preeclampsia-related module genes." (PMID 41958596, 2026). "Functional and rescue assays confirm that miR-142-3p negatively regulates RDH13, thereby suppressing trophoblast proliferation, invasion, and migration while promoting apoptosis, revealing a novel preeclampsia-related regulatory mechanism." (PMID 41958596, 2026). "We developed a 5-mRNA signature (termed PE5-signature) to diagnose preeclampsia from 38 DEGs using recursive feature elimination with a random forest supervised classification algorithm, including ENG, KRT80, CEBPA, RDH13 and WASH9P." (PMID 35774506, 2022).
breast carcinoma (1 paper, 2021). "Furthermore, we generated an expression risk score for each of the breast cancer patients in the METABRIC Discovery, Validation and TCGA sets using the seven genes RDH5, RDH8, RDH10, RDH11, RDH12, RDH13, RDH14." (PMID 33436820, 2021). "To explore the expression patterns of the seven genes RDH5, RDH8, RDH10, RDH11, RDH12, RDH13, RDH14 in normal tissues as well as breast cancer tissue, we first drew a heat map of the expression levels of the genes across normal human tissues from GTEx portal." (PMID 33436820, 2021).
gastric cancer (1 paper, 2021). A primary or metastatic malignant neoplasm involving the stomach. "our analysis implied that DNA hypomethylation may lead to induce the RDH13 and UCHL1 expression in gastric cancer, whereas DNA hypermethylation is able to cause decreasing expression of CLDN11 in gastric groups." (PMID 34322159, 2021). "We revealed that RDH13, CLDN11, TMTC1, UCHL1, and FOXP2 can serve as predictive biomarkers for gastric cancer treatment and the promoter methylation level of these five genes in serum could have prognostic and diagnostic functions in gastric cancer patients." (PMID 34322159, 2021). "Further, we identified 5 prognostic genes (RDH13, CLDN11, TMTC1, UCHL1, and FOXP2) in gastric cancer." (PMID 34322159, 2021).
lung adenocarcinoma (1 paper, 2024). A carcinoma that arises from the lung and is characterized by the presence of malignant glandular epithelial cells. "The correlation analysis exhibited a positive relationship between RDH13 and CCL28 in lung adenocarcinoma." (PMID 39075504, 2024).
retinopathy (2 papers, 2012 to 2020). "Rdh13 is also important in retinal biology, as Rdh13−/− mice suffer from acute light-induced retinopathy via the mitochondrial apoptosis pathway." (PMID 32151018, 2020).
cancer (1 paper, 2021). A tumor composed of atypical neoplastic, often pleomorphic cells that invade other tissues. "Collectively, these results provide a strong indication that RDH13 expression may be induced by cancer-induced reprogramming, resulting in RDH13 promoter hypomethylation within gastric ATM group." (PMID 34322159, 2021).
infection (1 paper, 2022). The state of being infected such as from the introduction of a foreign agent such as serum, vaccine, antigenic substance or organism. "COL1A2, RDH13, and RPS12 were down-regulated following infection with the mutant strain, whereas DEGs related to C-type lectins recognition and signaling mechanisms were up-regulated." (PMID 35215144, 2022).
RDH13 also shares sentences with these, for which no sentence is quoted: tumor (2 papers); convergent strabismus (1); geographic atrophy (1); Retinal dystrophy (1).